INS (insulin)
Diseases named in the same sentence as INS in open-access papers (continued):
Sharing a sentence is not in itself a finding about the gene and the disease.
Insulin resistance (continued). "Insulin resistance by the cells first results in excessive proliferation of the pancreatic beta cells in an effort to compensate and produce more insulin." (PMID 35887304, 2022). "They disrupt insulin signalling in peripheral tissues, supressing glucose uptake and utilization, and promote adipose tissue inflammation, and lipid induced insulin resistance." (PMID 36561568, 2022). "The important pathological features of T2DM are insulin resistance and impaired insulin secretion from pancreatic β-cells." (PMID 35355717, 2022). "Peroxynitrite leads to insulin resistance via the nitration of tyrosine residues on key proteins in the insulin-signaling pathway." (PMID 37123089, 2022). "Insulin resistance decreases the sensitivity of the physiological function of insulin and leads to type 2 DM." (PMID 36143007, 2022). "In obese patients, decreased insulin activity due to insulin resistance leads to the inhibition of TG lipolysis and increased TG degradation in the adipose tissue, causing boosted fatty acid liver release." (PMID 36145147, 2022). "Insulin resistance is an important physiological process essential during pregnancy to ensure sufficient fetal nutrition, and the physiological changes in insulin are excessive in women with GDM, usually as a result of β-cell impairment." (PMID 36072413, 2022). "Insulin resistance can be considered as a defect in the ability of insulin to facilitate glucose disposal and poor response to insulin in tissues, such as skeletal muscle, liver, and white adipose tissue." (PMID 36009505, 2022). "Insulin resistance is an earlier stage in the development of type 2 diabetes, and skeletal muscle, as the largest glucose consumption and insulin‐sensitive organ in the human body, is responsible for the disposal of ~2/3 of postprandial blood glucose." (PMID 35961942, 2022). "Fasting insulin has been considered the most feasible way of measuring insulin resistance; however, one main disadvantage of the method is the lack of accuracy or precision of available insulin assays." (PMID 35631177, 2022). "In the early stages of T2DM, enhanced secretion of insulin is indispensable to maintain blood glucose levels to overcome insulin resistance." (PMID 35414044, 2022). "Like T2DM, GDM has a complex pathology that is hallmarked by insulin resistance and inadequate insulin secretion resulting from pancreatic β-cell dysfunction." (PMID 36499008, 2022). "Characterization of changes in insulin sensitivity would provide insights into the effect of the diets on reversing insulin resistance and delaying type 2 diabetes." (PMID 35889947, 2022). "Elevated insulin levels, which represent insulin resistance, can promote cancer through the insulin-like growth factor-1 (IGF-1) pathway." (PMID 35626156, 2022). "Insulin resistance (IR) is a situation in which cells in the liver, fat, and muscles have weak responses to insulin and are unable to utilize glucose from the blood for consuming energy." (PMID 36572938, 2022). "Our data reveal a previously-unrecognized mechanism for IRS1 to mediate insulin signaling and to confer insulin resistance, which involves LLPS-mediated formation of IRS1 condensates." (PMID 35790738, 2022). "Insulin resistance can occur via dysfunctional BCAA catabolism or BCAA levels acting as signaling molecules hampering the insulin signaling pathways." (PMID 35931683, 2022). "In mice with overexpression of a UCP, a more potent uncoupler than UCP2 or UCP3 in skeletal muscle, an enhanced insulin action and resistance to weight gain and insulin resistance induced by the HFD were determined." (PMID 35323702, 2022). "At the pathophysiological level, type 2 diabetes (T2D) is primarily characterized by peripheral insulin resistance and progressive exhaustion/destruction of insulin producing pancreatic beta cells." (PMID 36615781, 2022).
Insulin resistance (continued). "Owing to the presence of active constituents in medicinal herbs, they have been reported to acquire some characteristic properties like pancreatic β-cell regeneration, insulin-releasing, and combating the problem of insulin resistance." (PMID 35345832, 2022). "Study has reported that young liver-specific Sirt1-knockout mice suffer from hyperglycaemia and gradually develop an impaired insulin response as they grow up, finally exhibiting whole-body insulin resistance." (PMID 35132380, 2022). "Two meta-analyses carried out consecutively in 2020 and 2022 showed that probiotics improve carbohydrate metabolism and insulin activity indicators, such as HOMA-IR and QUICKI, and can reduce the risk of insulin resistance in patients with GDM." (PMID 36296986, 2022). "Considering that our research was conducted in patients with T2DM, who generally had decreased insulin secretion and insulin resistance, the contradictory results can be understood." (PMID 36274973, 2022). "This is mainly due to bone protective effects of high insulin level as the result of insulin resistance, mechanical tension of excess weight on bones, and elevated leptin levels in T2DM patients with concurrent obesity." (PMID 36578470, 2022). "This fasting also impacts glucometabolic markers (e.g., adiponectin, leptin, insulin resistance, and serum insulin levels)." (PMID 35454343, 2022). "Risk factors, especially obesity, affect the balance between hormone-induced insulin resistance and increased insulin secretion, which consequently results in GDM." (PMID 36077491, 2022). "Our results also show the cilium-related regulation of insulin signaling in hypothalamic neurons, offering a potential new therapeutic avenue for obesity and insulin resistance." (PMID 35902579, 2022). "Despite that insulin resistance as manifested by acanthosis nigricans and higher insulin levels occur commonly in adolescents with PCOS and it is exacerbated by obesity; this is not recommended for the diagnosis of PCOS during adolescence." (PMID 36010282, 2022). "They trigger NF-κB and AP-1, produce IL-6 and TNF-α that affect insulin sensitivity by altering the expression of genes encoding IRS-1, GLUT-4, and PPAR-α and lead to insulin resistance." (PMID 36140983, 2022). "In comparison with the control group, the membrane translocation of GLUT4 stimulated by insulin decreased in states of insulin resistance." (PMID 36313766, 2022). "As this condition continues, insulin resistance is induced, blood insulin sensitivity is reduced, and the hyperglycemic state continues." (PMID 36558538, 2022). "Results showed that compared with the control group, both insulin levels and insulin resistance scores were higher in patients with UM or choroidal nevi." (PMID 36003786, 2022). "The earliest abnormality observed in insulin resistance is a decrease in insulin-induced glucose uptake in skeletal muscle and adipose tissue." (PMID 36555322, 2022). "We also found that the DAS was significantly associated with glycemic traits, such as FBG, glycated hemoglobin (HbA1c), insulin, and homeostatic model assessment of insulin resistance (HOMA‐IR)." (PMID 35142450, 2022). "We found a positive correlation between HOMA-IR and leptin levels, along with other risk factors for insulin resistance, such as triglycerides, FPG, insulin levels, WC, and BMI." (PMID 36143007, 2022). "ADM has several metabolic actions, including counteracting oxidative stress–induced insulin resistance and inhibition of insulin secretion from the pancreatic islets." (PMID 35681200, 2022). "Insulin resistance is a mechanism in which insulin-dependent cells (such as adipocytes) respond inappropriately to insulin." (PMID 36079784, 2022). "T2DM is characterized by peripheral insulin resistance and impairment of insulin production from pancreatic β-cells in a landscape of systemic inflammation." (PMID 35335211, 2022).
Insulin resistance (continued). "In our study, the 25OHD-S effects have improved insulin resistance and insulin sensitivity in peripheral tissues, attested by the HOMA index attenuation." (PMID 35930297, 2022). "These pro-inflammatory cytokines injure the insulin signaling and trigger insulin resistance, even aggravating ROS generation." (PMID 36139776, 2022). "While the largest body of evidence for a role of galectin-1 in insulin resistance is currently focused on the adipose tissue, galectin-1 is altered in many different cells in the insulin resistant state." (PMID 36295832, 2022). "Circulating concentrations of IGFBP-1, coupled with fasting levels of insulin, have been proposed as a more specific screening test for insulin resistance in children." (PMID 35586622, 2022). "Systemic insulin resistance promotes nonalcoholic fatty liver disease progression, which, in turn, exacerbates insulin action and eventually forms a vicious cycle." (PMID 35889860, 2022). "Eventually, higher compensatory levels of insulin must be released to lower blood glucose, which drives insulin resistance." (PMID 36128718, 2022). "SOCS-3 is not only a negative regulator of IL-6 signaling but also inhibits insulin signal transduction at the IRS protein level and causes hepatic insulin resistance." (PMID 35603204, 2022). "In turn, the phosphorylation level of Akt, the distal cascade in insulin signaling, is suppressed, and peripheral insulin resistance develops." (PMID 36613674, 2022). "This included lower fasting blood glucose, hemoglobin A1c (HbA1c), fasting serum insulin, and homeostatic model of insulin resistance (HOMA-IR)." (PMID 35316158, 2022). "Hyperinsulinemia can also decrease the expression of downstream insulin signaling mediators IRS1 and IRS2, which have been linked to insulin resistance." (PMID 35884888, 2022). "Although the molecular mechanisms and mediators governing HFD-mediated insulin resistance and inflammation are unclear, one protein of interest in regulating the insulin response is AhR." (PMID 36499198, 2022). "T2DM is characterized by chronic hyperglycemia due to insufficient insulin signaling due to defective insulin secretion and insulin resistance, and it is also related to increased endogenous glucose production (EGP) or glucagon." (PMID 35614469, 2022). "Insulin resistance, a harbinger of the metabolic syndrome, is a state of compromised hormonal response resulting from the dysregulation of a wide range of insulin-controlled cellular processes." (PMID 35440636, 2022). "Insulin resistance is evident in the current study by the significant increase in fasting blood glucose, insulin, HOMA-IR, atherogenic parameters (sd-LDL, ox-LDL, and Apo B/Apo A ratio)." (PMID 35565871, 2022). "When there is Insulin Resistance in the body, the target tissues start ignoring Insulin’s signal that is to get the glucose out of the bloodstream and put it into our cells." (PMID 35879737, 2022). "The average baseline level of C-peptide (0 min) was slightly higher in the severe group than in the moderate group, indicating a higher fasting insulin concentration, an indicator of systemic insulin resistance." (PMID 35343389, 2022). "The hydroethanolic extract from S. cumini leaves also improved hyperinsulinemia and insulin resistance by modulating ß-cell insulin release in monosodium L-glutamate (MSG)-induced obese rats." (PMID 35684249, 2022). "The authors observed that resveratrol supplementation improved insulin resistance in high-fat diet fed mice by restoring fasting blood glucose and insulin concentrations to nearly normal levels." (PMID 36687699, 2022). "Oxidative stress can induce insulin deficiency, and can produce large quantities of ROS to hinder insulin signaling transduction, thereby triggering insulin resistance." (PMID 35846289, 2022).
Insulin resistance (continued). "It is well known that short-term Intralipid/heparin infusion essentially increases FFA concentrations and leads to insulin resistance by reducing peripheral glucose uptake and down-regulating intracellular insulin signaling." (PMID 35215487, 2022). "A previous study has reported that East Asians have lower insulin secretion and insulin resistance than Caucasians." (PMID 36457559, 2022). "Glucose tolerance was unchanged or only slightly impaired in spite of severe insulin resistance, due to increased insulin secretion." (PMID 36175420, 2022). "SOCS3 can inhibit insulin secretion, and down-regulation of this gene promote insulin secretion, resulting in insulin resistance." (PMID 35606885, 2022). "Elevated blood level of FFAs is a signature in obesity and plays in crucial role in insulin resistance and inflammation in the insulin target tissues such as liver, adipose tissue, and skeletal muscle." (PMID 35936891, 2022). "In both diabetic groups, adiponectin was positively correlated with body mass index, glycated hemoglobin, insulin, homeostasis model assessment of insulin resistance, and microalbuminuria, while negatively correlated with estimated glomerular filtration rate." (PMID 36039271, 2022). "GK rats share a number of similarities with human type 2 diabetes, as they are characterized by both insulin resistance and impaired insulin secretory function." (PMID 36359885, 2022). "Expansion of β cell mass occurs under physiological (e.g., pregnancy) or pathological (e.g., obesity) conditions of insulin resistance, and these demand a commensurate rise in insulin output from the pancreatic β cells to maintain glucose homeostasis." (PMID 36107617, 2022). "During the follow-up period, insulin sensitivity increases, insulin resistance decreases with decreasing doses of drugs, increasing urea elimination and improving calcium-parathormone levels." (PMID 36402951, 2022). "The inhibition effect on proinflammatory factors decreases insulin resistance and stimulates insulin signaling." (PMID 36062167, 2022). "Insulin resistance is a primary reason characterized by reduced insulin activity despite its excessive levels in the blood, eventually leading to sustained hyperglycemia." (PMID 36005597, 2022). "Insulin resistance is characterized by impaired insulin activity, which is initially compensated for by higher circulating insulin levels." (PMID 35646861, 2022). "Insulin resistance occurs when insulin is ineffective in getting plasma glucose to enter a body’s cells and be used for energy by the cells, even when there is enough insulin in the blood." (PMID 35268696, 2022). "The combination of insulin therapy and oral glucose-lowering drugs (GLDs) is a potential approach in T2D patients with severe insulin resistance and poor glycemic control." (PMID 36015100, 2022). "Insulin resistance is defined in physiological terms as requiring higher concentrations of insulin to trigger the physiological effects formerly induced by lower concentrations." (PMID 36419769, 2022). "In our cross-section study, we found the insulin resistance (lower ISI and CSI) and a delayed peak of insulin secretion were significantly associated with the aggressiveness of DTC." (PMID 35299970, 2022). "It was shown that tau protein phosphorylation increased significantly in an animal model of insulin resistance induced by fructose; in AD transgenic mice, insulin resistance induced by diet facilitated brain Aβ formation." (PMID 35615716, 2022). "Increasing PA categories were positively associated with age, male sex, BMI, systolic blood pressure, alcohol intake, and glucose levels and better insulin resistance markers (lower insulin level and HOMA-IR score)." (PMID 35382785, 2022). "Insulin resistance in the hippocampal tissue is considered one of the important triggers for the decline in learning and memory function; therefore, activating the insulin signaling pathway can rescue impaired learning and memory capacity." (PMID 35745162, 2022).
Insulin resistance (continued). "Being a critical upstream phosphatase, the role of PHLPP in neuronal insulin signaling and insulin resistance is largely missing." (PMID 36376971, 2022). "In this study, we observed a significant decrease in insulin concentration and level of insulin resistance in the Allium group." (PMID 36352899, 2022). "As a first-line treatment for insulin resistance, MET can improve insulin sensitivity and regulate blood sugar levels, thereby alleviating insulin resistance, which can also reduce androgen levels and improve ovulation." (PMID 35698127, 2022). "In order to determine the effects of corticosterone or mirabegron on insulin resistance, plasma glucose and insulin concentrations were measured." (PMID 35510321, 2022). "Reversal of the metabolic phenotype upon liver-specific reconstitution of CEACAM1 further demonstrates the primary role of hepatic insulin clearance in the pathogenesis of insulin resistance." (PMID 36009446, 2022). "For instance, the ablation of Nrf2 in adipocytes leads to enhanced insulin resistance, while Nrf2 deletion in hepatocytes results in increased insulin sensitivity." (PMID 36555392, 2022). "Incretin peptides are of great importance in glucose homeostasis as they increase insulin secretion by β-cells, reduce insulin resistance as well as inhibit β-cell apoptosis and stimulate β-cell proliferation." (PMID 36077491, 2022). "We also observed a significant glucose intolerance and increased levels of fasting insulin, illustrating insulin resistance, which was corroborated by the increased HOMA-IR." (PMID 36012191, 2022). "Adequate vitamin D has a certain effect on promoting insulin secretion and reducing insulin resistance." (PMID 36079784, 2022). "The main pathological features of diabetic patients are hyperinsulinaemia and insulin resistance, and the concentration of insulin in the blood is increased." (PMID 36217741, 2022). "modulated insulin resistance (ko04931), the insulin signaling pathway (ko04910), starch and sucrose metabolism (ko00500), and other associated pathways." (PMID 36290180, 2022). "In support of this, higher levels of 2 h glucose—predominantly mirroring peripheral insulin resistance and/or failure in 2nd-phase insulin secretion—are a strong predictor for failure to achieve NGR in our trial." (PMID 36432409, 2022). "In the study, the use of the supplement did not significantly influence fasting glucoseorHbA1c but it prevented an increase in serum insulin concentration and resulted in an improvement in insulin resistance." (PMID 36296986, 2022). "LJF reduced HOMA-IR index and increased ISI index in T2DM mice, indicating that LJF improved the balance between insulin resistance and insulin sensitivity, which was same with Arimillariella tabescens polysaccharides." (PMID 36613249, 2022). "Insulin resistance is a complex and highly prevalent metabolic disorder, which is mainly due to the inability of multiple insulin target sites, including but not limited to skeletal muscle, liver, and adipose tissue, to respond to insulin." (PMID 35055114, 2022). "Insulin resistance is a state in which higher than normal concentration of insulin is needed for individuals, leading directly to hyperinsulinemia, as daily insulin dose in patients with MetS were higher to those in the without MetS group in our study." (PMID 36204109, 2022). "Pathways with upregulated DEGs are involved in insulin resistance whereas downregulated inflammatory pathways as revealed by KO are responsible for insulin sensitivity." (PMID 36440192, 2022). "Mitochondrial OxS plays a critical role in the development of insulin resistance and insulin hypersecretion." (PMID 36589440, 2022). "In an insulin resistant HepG2 cell model, the PPARδ agonists enhanced exenatide efficacy on insulin resistance, with the expression of GLP-1R being up-regulated markedly." (PMID 36051387, 2022).